GDF15 (growth differentiation factor 15)
Diseases named in the same sentence as GDF15 in open-access papers (continued):
Sharing a sentence is not in itself a finding about the gene and the disease.
depression (continued). "Regarding associations among the core biomarkers and depression severity, GDF11 was negatively correlated with GDF15 (r=-0.643, p<0.01) and HAMD-17 scores (r=-0.663, p<0.01), while showing a positive correlation with TGF-β1 (r=0.493, p<0.01)." (PMID 40958792, 2025). "The results revealed that GDF15 possessed the most outstanding discriminative ability for predicting depression, with an area under the curve (AUC) of 0.9698 [95% CI (0.9488-0.9907), p< 0.0001]." (PMID 40958792, 2025). "This study provides compelling evidence for the dysregulation of TGF-β superfamily members in depression and highlights the potential of GDF15, TGF-β1, and GDF11 as promising biomarkers for both diagnosis and severity assessment." (PMID 40958792, 2025). "Here, older adults with both-cognitive-frailty-and-depression have significantly higher GDF15 than the other two groups." (PMID 37715843, 2024). "In the European study to establish bioMARKers of human AGEing (MARK-AGE), the relationship between plasma GDF15 levels, cognitive frailty, and depression was explored in 2736 participants, including individuals who were 55+ years and younger adults." (PMID 38337499, 2024). "Here it has been suggested that GDF15 can be a biological pathway between depression and cognitive aging." (PMID 37715843, 2024). "Cognitive frailty, depression, age and GDF15 were significantly related within the whole study sample." (PMID 37715843, 2024). "Serum levels of testosterone, estradiol, and depression risk biomarkers (thyroid hormone, lipids, hs-CRP, Tenascin-C [TNC], GDF15, KLF4, Gas6, and sgp130) were measured." (PMID 36635686, 2023). "In conclusion, our study indicates that serum GDF-15 levels are related to sex hormone levels and accompanying depressive symptoms, shedding new light on our understanding of depression." (PMID 34942914, 2021). "Cytokines, such as Growth differentiation factor-15 (GDF-15), may play a role in the pathogenesis of malnutrition and depression." (PMID 40365427, 2025). "Growth differentiation factor-15 (GDF15) might be involved in the development of cognitive frailty and depression." (PMID 37715843, 2024). "GDF15 has also been reported to promote simultaneous astrocyte remodeling and tight junction strengthening at the blood–brain barrier (BBB), which is closely associated with the occurrence and development of depression." (PMID 36635686, 2023). "Inhibiting the deleterious effects of GDF-15 in neuropsychiatric disorders by balancing the T/E2 ratio may be a novel strategy for the treatment of depression." (PMID 34942914, 2021). "In addition, similarly to previous reports, we found that depression, a common neurodegenerative disorder, is also strongly correlated with the level of serum GDF-15." (PMID 34942914, 2021). "So, changing the level of GDF-15 by regulating the proportion of sex hormones may play a key role in the prognosis and treatment of depression." (PMID 34942914, 2021). "Consequently, with growing evidence, a relationship between progress and prognosis of depression and the serum GDF-15 levels has become generally accepted." (PMID 34942914, 2021). "Moreover, up-regulated GDF-15 levels can increase the inflammatory response, and both, inflammation and oxidative stress act synergistically, rendering the pathogenesis of depression more complex." (PMID 34942914, 2021). "Meanwhile, growing research has shown the value of serum GDF-15 in augmenting the diagnosis of depression and proved that high GDF-15 levels increase the mortality of depression, which may affect the progress and prognosis of depression." (PMID 34942914, 2021). "Additionally, GDF15 has also been reported to promote astrocyte remodeling and strengthen tight junction at the blood–brain barrier (BBB), which is closely associated with the occurrence and development of depression." (PMID 40958792, 2025).
depression (continued). "Our results indicate that the depression-defining SDS score might independently be associated with GDF15, whereas the cognitive frailty-defining GCF score might not be independently related with GDF15." (PMID 37715843, 2024). "An index of SASP proteins was associated with antidepressant response to late-life depression in a nonrandomized trial of 416 older adult participants with major depressive disorder, but neither GDF-15 nor IGFBP-2 were included for consideration in the development of their SASP index." (PMID 37982669, 2024). "Thus, disturbed sex hormones may further contribute to the change of GDF-15, ultimately leading to depression." (PMID 34942914, 2021). "Thus, clarification of this relationship is worth pursuing further since GDF-15 could emerge as a valuable biomarker for the evaluation of depression." (PMID 34942914, 2021). "Adults with both-cognitive-frailty-and-depression are significantly older, have significantly lower GCF scores and higher SDS scores, and have significantly higher plasma GDF15 than adults of the other two groups." (PMID 37715843, 2024). "As far as we know, this is the first study to specifically focus on adolescent populations in this context.Our findings suggest that TGF-β superfamily members- particularly GDF15, TGF-β1, and GDF11-may play important roles in the pathophysiology of depression." (PMID 40958792, 2025). "After controlling for age, gender and BMI, the analysis revealed that TGF-β1 and GDF11 were significant negative predictor of depression severity (both p <0.001), while GDF15 showed significant positive predictive relationship (p<0.001)." (PMID 40958792, 2025). "Collectively, these results suggest that elevated GDF15 may reflect an overactive inflammatory response and impaired BBB homeostasis, ultimately contributing to the development and progression of depression." (PMID 40958792, 2025). "Studies investigating the relation of circulating GDF15 with combined cognitive frailty and depression are lacking, so far, especially in studies including both older and younger adults." (PMID 37715843, 2024). "Cognitive frailty and depression may coexist and pathophysiological mechanisms overlap, but studies evaluating the relationship of circulating GDF15 with combined cognitive frailty and depression are lacking." (PMID 37715843, 2024). "Moreover, high GDF15 is significantly age, BMI, sex, comorbidities and hsCRP-independently related only to self-rated depression scores but not to GCF scores in adults of the whole study population and in older adults." (PMID 37715843, 2024). "Interestingly, age was still associated with both-cognitive-frailty-and-depression as well as GDF15 in our older participants, but not with global cognitive functioning and self-rated depression scores in adjusted regression models." (PMID 37715843, 2024). "We speculate that individuals with sex hormone imbalance could stimulate GDF15 expression, and it shows a negative effect to promote the development of depression, including the induction of inflammation and oxidative stress." (PMID 36635686, 2023). "Sex distribution was also similar between the three cognitive frailty-depression groups without a significant association with both-cognitive-frailty-and-depression; however, sex was significantly associated with GFC and SDS scores as well as with GDF15 within the adjusted regression models." (PMID 37715843, 2024).
iron deficiency (17 papers, 2010 to 2025). "Predictive logistic regression models were built and post estimation receiver operator characteristics were determined to evaluate diagnostic validity of hepcidin and GDF-15 for iron deficiency anaemia." (PMID 37649102, 2023). "Predictive logistic regression models were built and post estimation receiver operator characteristics were determined to evaluate diagnostic validity of hepcidin and GDF-15 for absolute and functional iron deficiency anaemia." (PMID 32993549, 2020). "Both GDF-15 (adj OR: 1.0003, 95%CI: 1.0001–1.0005, P = 0.017) and hepcidin (adj OR: 1.003, 95%CI: 1.0004–1.0055, P = 0.023) were associated with iron deficiency anaemia after multiple linear regression modelling." (PMID 32993549, 2020). "The results above show that, while stimulated erythropoiesis leads to an increase in Erfe and Gdf15 expression, much higher levels are reached when the iron supply to erythroid precursors is limited, as in iron deficiency." (PMID 28135344, 2017). "While the genes encoding erythroferrone and Gdf15 were upregulated in the bone marrow and spleen in most of the models examined, the highest levels were seen with iron deficiency." (PMID 28135344, 2017). "Significant induction of GDF-15 has also been observed in individuals with iron deficiency." (PMID 27043030, 2016). "It is not clear if growth differentiation factor-15 (GDF-15) or hepcidin are useful as early markers of iron deficiency anaemia (IDA) among non-dialysis CKD patients." (PMID 32993549, 2020). "In this study GDF-15 was related hsCRP and NGAL (neutrophil gelatin associated lipocalin) in patients without functional iron deficiency, while in patients with functional iron deficiency, GDF-15 was related to serum iron and transferrin saturation." (PMID 27043030, 2016). "First, GDF-15 may be an important mediator in a negative feedback pathway where it suppress high hepcidin levels in CKD patients with iron deficiency." (PMID 37649102, 2023). "First, GDF-15 may be an important mediator in a negative feedback loop whereby it increases to suppress high hepcidin levels in CKD patients with iron deficiency." (PMID 32993549, 2020).
hyperemesis gravidarum (16 papers, 2018 to 2026). Severe, intractable vomiting during pregnancy (usually the first trimester) accompanied by dehydration, weight loss, and electrolyte imbalances. "GDF15 is involved in promoting embryo endometrial invasion and has recently been linked to causing hyperemesis gravidarum in humans." (PMID 40188483, 2025). "GDF15, a hormone acting on the brainstem, has been implicated in the nausea and vomiting of pregnancy, including its most severe form, hyperemesis gravidarum (HG), but a full mechanistic understanding is lacking." (PMID 38092039, 2024). "The gene, growth differentiation factor-15, which codes for a nausea and vomiting hormone produced by the placenta, is the greatest genetic risk factor for hyperemesis gravidarum, and therapies are currently in clinical trials in cancer." (PMID 36536797, 2023). "High serum GDF15 levels during pregnancy have previously also been linked to nausea and hyperemesis gravidarum, and in our previous study we showed an association with beta-cell function as measured by HOMA-B." (PMID 34043633, 2021). "From the genetic perspective, among European women, variants in placenta and appetite genes such as GDF15 and IGFBP7 have been associated with hyperemesis gravidarum as has circulating levels of GDF15." (PMID 34420517, 2021). "Several observational studies then found that higher concentrations of circulating GDF15 is associated with more severe cases of NVP, complementing the findings that the gene loci for GDF15 is associate with hyperemesis gravidarum." (PMID 39015511, 2024). "The association of rs1058587 with adiposity traits and hyperemesis gravidarum raises the possibility that GDF15 exerts a causal effect that is not mediated by altered plasma levels, such as via altered proteoforms and/or altered GFRAL binding." (PMID 35916366, 2022). "In fact, the only non-chronic disease situation described, in which GDF15 is up regulated, is hyperemesis gravidarum associated with intense nausea and vomiting in early pregnancy." (PMID 32723474, 2020). "Growth differentiation factor-15 (GDF15), a stress-responsive cytokine of the transforming growth factor-β superfamily, is elevated in cancer cachexia, chemotherapy-induced nausea, and hyperemesis gravidarum, making it both a biomarker and a therapeutic target." (PMID 42104019, 2026).
Parkinson disease (16 papers, 2016 to 2026). A progressive degenerative disorder of the central nervous system characterized by loss of dopamine producing neurons in the substantia nigra and the presence of Lewy bodies in the substantia nigra and locus coeruleus. "We aimed to investigate the causal relationships between GDF-15 and Alzheimer’s disease (AD), Parkinson’s disease (PD), and amyotrophic lateral sclerosis (ALS)." (PMID 34484296, 2021). "Previous MR studies on Alzheimer’s disease suggest potential causal associations with BIN1, CCL27, C3, CD33, CD4 T cells, GDF-15 and SVEP1, whereas MR studies on Parkinson’s disease suggest a potential causal association with GPNMB, IL-6 and MIP1b." (PMID 37118290, 2022). "GDF15 was important for the neuroprotection of dopaminergic neurons in a mouse model of Parkinson's disease." (PMID 35068064, 2022). "There was a demonstration that GDF15 may participant in the etiology of Parkinson's disease through the activation of chemokine receptor 4 (CXCR4)." (PMID 36635686, 2023). "Therefore, this study provides a range of pathophysiological insights into PD and indicates that GDF15 is a potentially promising therapeutic agent for the treatment of parkinsonism." (PMID 35721026, 2022). "However, none of these studies described the levels of GDF15 for AD patients, but rather for Parkinson’s disease or Lewy Body Dementia." (PMID 33131010, 2021).
type 1 diabetes (16 papers, 2016 to 2025). "Serum levels of soluble intercellular adhesion molecule 1 (sICAM-1) and GDF15 were also higher in participants with type 1 diabetes." (PMID 41285865, 2025). "GDF15 was elevated at baseline in the type 1 diabetes group." (PMID 41285865, 2025). "However, the role of GDF15 in autoimmune disease is controversial, as demonstrated in type 1 diabetes, where it was shown to have a possible protective role." (PMID 41303556, 2025). "In addition, in type 1 diabetes, GDF15 may enhance insulin production by protecting the pancreas from inflammation." (PMID 34113829, 2021). "However, because GDF15 can protect the pancreas from inflammation at least in type 1 diabetes, and because DHODH inhibitors are used against autoimmune diseases, it is still possible that to some extent, DHODH inhibitors could protect the pancreas from inflammation." (PMID 34113829, 2021).
malnutrition (15 papers, 2020 to 2026). Inadequate nutrition resulting from poor diet, malabsorption, or abnormal nutrient distribution. "Both local expression and blood levels of GDF‐15 have been linked to mitochondrial dysfunction, anorexia, malnutrition and muscle wasting, core pathophysiological contributors to frailty." (PMID 41560403, 2026). "The present study investigated the effectiveness of the serum GDF-15 for predicting malnutrition and all-cause mortality, as well as its correlation with nutrition/inflammation laboratory measurements in HD patients." (PMID 34247467, 2021). "Furthermore, serum GDF15 levels were significantly increased in AECOPD patients with malnutrition and were identified as an independent risk factor for AECOPD in patients with malnutrition." (PMID 39050134, 2024). "Furthermore, serum GDF15 levels were an independent risk factor for malnutrition in patients with AECOPD (OR = 1.010, 95% CI, 1.003∼1.016)." (PMID 39050134, 2024). "Other treatment-related complications associated with inflammation such as fever, infection, or malnutrition itself may also result in GDF15 elevation, thus requiring future study for each of these specific risk factors." (PMID 38146512, 2023). "Thus, the present study aimed to determine if there is an association between the GDF-15 level and nutrition parameters and malnutrition/inflammation scoring indexes in HD patients." (PMID 34247467, 2021). "The underlying mechanism by which GDF15 contributes to malnutrition in AECOPD remains unclear." (PMID 39050134, 2024). "When elevated GDF15 was combined with low albumin (< 36.15 g/L), the model’s predictive accuracy for malnutrition significantly improved (AUC = 0.935), outperforming single indicators." (PMID 40697555, 2025). "ROC analysis showed that serum GDF-15 levels had a lower sensitivity than serum albumin, but a higher specificity in predicting malnutrition in patients with AECOPD." (PMID 39050134, 2024). "This study aimed to assess the predictive value of serum GDF15 for malnutrition in patients with AECOPD and to determine the optimal cut-off value for its use in clinical practice." (PMID 39050134, 2024). "In this study, we separately analyzed the predictive efficacy of serum GDF-15 and albumin levels in patients with malnutrition and AECOPD." (PMID 39050134, 2024). "An additional aim was to differentiate mortality according to HD patients’ malnutrition scores and serum GDF-15 levels." (PMID 34247467, 2021). "The present findings show that according to MIS, the GDF-15 level significantly differentiated malnutrition/inflammation with a cut-off 40.28 ng mL–1—this cut-off has not been previously reported." (PMID 34247467, 2021). "The serum GDF-15 level significantly differentiated malnutrition/inflammation according to MIS (AUROC: 0.60; 95% CI: 0.5120.689; p-= 0.031)." (PMID 34247467, 2021). "The cutoff value for GDF-15 was 40.28 ng mL–1 with sensitivity of 61% and specificity of 39% for predicting malnutrition." (PMID 34247467, 2021). "We excluded patients with all obvious infectious states, known cardiac problems, and inflammatory conditions to make GDF-15 reliable in the assessment of malnutrition, but all above finding needs to be confirmed by larger-scale studies." (PMID 34247467, 2021). "Area under a receiver operating characteristic (AUROC) was performed to explore the ability of the serum GDF-15 level to predict malnutrition according to the MIS, PNI, and CONUT scores." (PMID 34247467, 2021). "Serum GDF15 levels could be used as a potential biomarker in the prediction of malnutrition in patients with AECOPD, offering a guidance for future clinical evaluation of malnutrition." (PMID 39050134, 2024). "Therefore, serum GDF15 levels combined with serum albumin levels were used to predict AECOPD malnutrition in patients, and the findings revealed a high sensitivity and specificity, with an AUC of 0.935." (PMID 39050134, 2024).